PTH (parathyroid hormone)
Diseases named in the same sentence as PTH in open-access papers (continued):
Sharing a sentence is not in itself a finding about the gene and the disease.
Hypercalcemia (continued). "It is clinically characterised by mild to moderate parathyroid hormone dependent hypercalcaemia, an autosomal dominant pattern of inheritance, and a normal to reduced urinary calcium excretion in spite of high serum calcium." (PMID 36536367, 2022). "Pediatric primary hyperparathyroidism (PHPT) is an uncommon endocrine disorder secondary to an increased secretion of parathyroid hormone (PTH), with an incidence of 2–5 per 100 000 children, responsible for hypercalcemia and hypophosphatemia." (PMID 36090548, 2022). "After therapy, patients should be monitored for PTH and calcium levels for at least a year and checked for the presence of any hypercalcemia symptoms." (PMID 36013465, 2022). "A 50-year-old man was diagnosed with pHPT in 2009 due to knee pain, polydipsia, polyuria, hypercalcemia (4.4 mmol/L), severely elevated PTH (more than 2,000 pg/ml), and a right upper parathyroid mass." (PMID 36303876, 2022). "Awareness must be increased among clinicians that in the event of hypercalcemia with low PTH concentrations and in patients with nephrolithiasis and/or nephrocalcinosis, pathogenic CYP24A1 mutations should be considered as a potential underlying disease." (PMID 35745247, 2022). "In the absence of reliable indicators of malignancy, current guidelines recommend considering a diagnosis of PC when PTH is markedly elevated and hypercalcemia severe (strong recommendation; low-quality evidence)." (PMID 36497335, 2022). "Information on the levels of calcium and PTH, as well as the effect of hypercalcemia treatment on tumor burden, survival rates, renal disease, and bone mineral density associated with PCs are not available." (PMID 35326576, 2022). "Primary hyperparathyroidism (PHPT) is a well-defined disorder characterized by hypercalcemia and elevated levels of parathyroid hormone (PTH)." (PMID 36187131, 2022). "These 3 individuals displayed symptomatic PTH-dependent hypercalcemia with hypocalciuria and were, thus, clinically suspected of having AHH." (PMID 36099030, 2022). "Of 72 patients with hypercalcemia unrelated to PTH, 15 (20.8%) met the criteria for the diagnosis of Ca supplementation syndrome (renal failure, metabolic alkalosis, elevated serum bicarbonate and taking Ca/vitamin D supplements)." (PMID 36500243, 2022). "Tertiary hyperparathyroidism (HPT) is a rare condition, in which patients develop autonomous parathyroid hyperfunction leading to persistent hypercalcemia and elevated serum PTH." (PMID 35497370, 2022). "Hypercalcemia during pregnancy is relatively rare and its further differential diagnosis is dependent on the prevailing parathyroid hormone (PTH) level." (PMID 35745247, 2022). "Primary hyperparathyroidism (PHPT) is an endocrine disorder characterized by increased release of calcium from skeletal hydroxyapatite, leading to hypercalcemia due to an inappropriately normal or elevated plasma parathyroid hormone (PTH) level." (PMID 35165625, 2022). "This subset of patients not only have the classical symptoms of hypercalcaemia and suppressed PTH but also exhibit hypophosphatemia due to kidney phosphate wasting." (PMID 33990852, 2022). "Primary hyperparathyroidism was suggested by hypercalcaemia, elevated parathyroid hormone level, hypercalciuria, nephrolithiasis on abdominal computed tomography scan and enlarged parathyroid gland on computed tomography pulmonary angiogram." (PMID 36176950, 2022). "Of 135 034 patients with hypercalcemia, 54 946 (40.7%) underwent further evaluation via obtaining PTH levels." (PMID 36574247, 2022). "In our in vivo model, we found that, in animals with constant levels of PTH, hypercalcemia induced a higher increase in FGF23 levels when vitamin D signaling was intact." (PMID 35807756, 2022). "Reported criteria for surgery varied widely between studies and included PTH levels, hypercalcaemia, hyperphosphataemia, symptoms refractory to medical treatment, enlarged parathyroid glands on imaging and/or KDIGO guideline criteria." (PMID 35179187, 2022).
Hypercalcemia (continued). "There are also few case reports of penile carcinoma presenting with hypercalcemia due to ectopic production of parathyroid hormone." (PMID 35913439, 2022). "These conditions are characterized by elevated serum PTH levels and subsequent bone disease, however only moderate hypercalcemia." (PMID 35566721, 2022). "Hypercalcemia also suppresses parathyroid hormone (PTH) secretion and then increases bicarbonate reabsorption." (PMID 35800648, 2022). "For patients with both hypercalcemia and hyperphosphatemia, CaMs is a reasonable choice in lowering the PTH level in comparison with the vitamin D analog." (PMID 36015101, 2022). "Sixteen (22%) of 74 patients with hypercalcemia and elevated PTH used either active vitamin D or calcium carbonate/acetate." (PMID 34668028, 2022). "This corresponds to an overall proportion of 18% of all hypercalcaemia patients with a PTH-independent elevation of serum calcium." (PMID 36427118, 2022). "Other causes of hypercalcemia in cases of RCC include medications like premarin, lytic bone lesions, and ectopic PTH secretion." (PMID 35913439, 2022). "Among the women with mild PHPT, hypercalcemia with PTH within the upper part of the reference range was present in 3 women at some time during follow-up (patients no 7–9)." (PMID 34647149, 2022). "Laboratory tests showed aregenerative, normocytic-normochromi anemia, hypercalcaemia (163mg/l), renal failure, creatinine (22mg/l), glomerular filtration rate 26 ml/min and low parathyroid hormone (PTH) (9.9pg/ml)." (PMID 35734323, 2022). "Primary hyperparathyroidism is usually characterized by hypercalcemia, which occurs due to excessive autonomous secretion of parathyroid hormone (PTH) and is three to four times more likely to be found in women aged 50 to 65 years." (PMID 35863283, 2022). "Major stimuli for the synthesis of PTH in the parathyroid glands are hypocalcemia, low 1,25(OH)2D levels, and hyperphosphatemia, whereas hypercalcemia and hypophosphatemia suppress PTH levels." (PMID 34910242, 2022). "Cinacalcet (a calcimimetic agent which directly lowers PTH levels) should be considered in patients with resistant hypercalcemia as a result of PTH over production." (PMID 34648136, 2022). "During post-operative follow-up, a patient in the open group experienced hypercalcemia and abnormal PTH 10 months after operation." (PMID 36338640, 2022). "A laboratory workup revealed hypokalemia, hypomagnesemia, hypercalcemia, and a high parathyroid hormone level." (PMID 35795477, 2022). "A 43-year-old man was diagnosed with pHPT in 2011 due to polydipsia and polyuria, hypercalcemia, severely elevated PTH, and a right parathyroid mass." (PMID 36303876, 2022). "Individuals were diagnosed with PHPT if they presented with hypercalcemia and elevated or inappropriately normal circulating PTH." (PMID 35038313, 2022). "By the 10th week of gestation, PTH is synthesized by the fetal parathyroid gland, but circulating concentrations are low during fetal life due to relative hypercalcemia dictated by the CaSR receptor (Taylor‐Miller & Allgrove, 2021)." (PMID 36514767, 2022). "The hallmark of hyperparathyroidism is hypersecretion of parathyroid hormone (PTH) which results in hypercalcemia and hypophosphatemia." (PMID 36544116, 2022). "Some patients were treated preoperatively with bisphosphonates, because of high hypercalcemia or hypercalcemic crisis, so that their preoperative calcium and PTH levels were already lowered." (PMID 35945299, 2022). "Although lithium is considered the gold-standard treatment for bipolar disorder (BD), it is associated with a variety of major endocrine and metabolic side effects, including parathyroid hormone (PTH) dependent hypercalcemia." (PMID 36153583, 2022). "At the age of 32 years, he presented with hypercalcemia (11 mg/dL) with extremely high serum intact PTH (4640 pg/mL) and ALP (5983 U/L) levels, although with normal serum phosphorus levels (3.1 mg/dL)." (PMID 35497370, 2022).
Hypercalcemia (continued). "Compared to parathyroid adenoma, parathyroid cancer is more likely to be associated with marked levels of serum parathyroid hormone (PTH) and hypercalcemia with severe clinical manifestations." (PMID 35547459, 2022). "Pathogenic mutations of CYP24A1 lead to an impaired catabolism of vitamin D metabolites and should be considered in the differential diagnosis of hypercalcemia with low parathyroid hormone concentrations." (PMID 35745247, 2022). "There are some limitations to the present study because SHPT-associated vascular disease is a complex process involving interactions of primary disease, hypercalcemia, hyperphosphatemia, and parathyroid hormone abnormalities." (PMID 35369318, 2022). "Primary hyperparathyroidism (PHPT) is characterized by overproduction of parathyroid hormone and subsequent hypercalcemia." (PMID 35586626, 2022). "The adverse events (AEs) and serious AEs were more common in the teriparatide group than in the alendronate group, which were mainly teriparatide-related hypercalcemia, elevated alkaline phosphatase or parathyroid hormone, dizziness, and arthralgia." (PMID 35900607, 2022). "Suspicion of PC is appropriate in the presence of severe hypercalcemia, elevated parathyroid hormone level, and a mass observed either during imaging or intraoperatively." (PMID 35863283, 2022). "The biochemical assays revealed hypercalcaemia (2.76 mmol/L), hypophosphatemia (0.70 mmol/L), and elevated parathyroid hormone (PTH) levels (134.60 pg/mL)." (PMID 35945539, 2022). "This is a rare genetic disorder in which catabolism of vitamin D metabolites is impaired, leading to hypercalcemia, low PTH concentrations, and relatively high serum 25(OH)D concentrations along with an increased risk of nephrolithiasis." (PMID 35406098, 2022). "The indications for bone biopsy were hypercalcemia combined with elevated PTH levels in 68 (62%) patients and normocalcemia with elevated PTH levels in 38 (35%) patients, respectively." (PMID 35349587, 2022). "In the indication group with only elevated PTH levels, five (12%) patients proceeded to parathyroidectomy, while 30 (40%) patients with hypercalcemia and elevated PTH levels were operated." (PMID 34668028, 2022). "The third patient with AHH was an 87-year-old man with a disturbed consciousness in whom PTH-dependent hypercalcemia with hypocalciuria was revealed (cCa, 14.3 mg/dL; iP, 2.2 mg/dL; Cre, 0.97 mg/dL; intact PTH, 32 pg/mL; and FECa, 0.18%)." (PMID 36099030, 2022). "It is noted that the patient’s bloody fluid in the cyst contained 19,960,000 pg/mL of intact-PTH, and its overflow into blood stream resulted in hyperparathyroidism and hypercalcemia." (PMID 36544116, 2022). "There are also studies in the literature reporting that EAT thickness is increased in patients with PHPT, unlike our study, and in one of these studies, it was reported that EAT thickness was correlated with serum PTH level and hypercalcemia." (PMID 36326370, 2022). "Most of the reported cases with active parathyroid tumor had severe hypercalcemia and elevated PTH levels to up 100 times normal levels." (PMID 36188029, 2022). "Interleukin-1 has been shown to participate in parathyroid cell function and secretion of PTH, and an interleukin-1 receptor antagonist to be able to regulate hypercalcemia." (PMID 36615752, 2022). "Hypercalcaemia results from intestinal hyperabsorption and is accompanied by suppressed intact PTH and hypercalciuria." (PMID 33990852, 2022). "Serum cortisol and its circadian rhythm can be abnormal in the presence of hypercalcemia and high PTH." (PMID 35370956, 2022). "Routine investigations were significant for hypercalcaemia, corrected calcium 3.19 mmol/L (2.21-2.52mmol/L), elevated parathyroid hormone of 84pg/ml (15-65pg/ml) and a low 24-hour urine calcium of 0.75mmol/24 (2.50-7.50mmol/24)." (PMID 36536367, 2022).
Hypercalcemia (continued). "FHH is a rare, genetically heterogeneous condition clinically characterised by mild to moderate parathyroid hormone (PTH) dependent hypercalcaemia, an autosomal dominant pattern of inheritance, and normal to reduced urinary calcium excretion." (PMID 36536367, 2022). "Suspicion of PC is appropriate in the presence of severe hypercalcemia (>14 mg/dL), high level of PTH (3 to 10 times the upper limit of normal), and a large mass, observed either during imaging or intraoperatively." (PMID 35863283, 2022). "Neonatal hypercalcaemia can be due to maternal or neonatal factors and can be divided into high or low PTH disorders." (PMID 33990852, 2022). "Although diagnosis before surgery is difficult, clinicians should suspect hyperparathyroid patients with a palpable neck mass, severe hypercalcemia, a noticeable rise in serum PTH level, and metabolic complications." (PMID 36532647, 2022). "While hypercalcemia due to malignancy is often brought about by PTHrP production in adults, PTH-producing tumors are quite rare in clinical practice." (PMID 36544116, 2022). "Mild PHPT (defined by moderate hypercalcemia with respect to normal but inappropriate PTH level, or elevated PTH level alone) is now the most common form of PHPT, accounting for about 80% of cases." (PMID 35268464, 2022). "A 29-year old woman was initially evaluated for parathyroid hormone (PTH)-dependent hypercalcemia in 2013." (PMID 33499837, 2021). "Primary hyperparathyroidism (PHPT) is a disease characterized by hypercalcaemia and elevated or inappropriately normal serum level of parathyroid hormone (PTH) due to parathyroid adenoma, hyperplasia or rarely cancer." (PMID 33957725, 2021). "Active vitamin D analogs should be titrated to maintain PTH within the normal range but also to avoid hypercalcemia, hypercalciuria and kidney stone formation." (PMID 33815294, 2021). "We highlighted a wider phenotype depending on vitamin D intakes, from a balanced state with normal or high normal serum calcium and hypercalciuria to an unbalanced state with hypercalcemia and hypercalciuria, but consistent low PTH." (PMID 34721296, 2021). "Less than 1% of hypercalcemia is related to elevated secretion of 1.25 hydroxyvitamin D and ectopic PTH secretion." (PMID 33832072, 2021). "In those patients, laboratory examinations mostly demonstrated a milder degree of hypercalcemia, but suppressed PTH levels were similar to those in infants with IIH." (PMID 34858904, 2021). "Previous studies have investigated several predisposing factors for papillary thyroid cancer in PHPT patients, such as the tumor promoting effect of PTH, the goitrogenic effect and increased mitotic activity induced by hypercalcemia and neck irradiation." (PMID 33957725, 2021). "Previous studies have uncovered several susceptible factors of PTC in PHPT, such as the tumor-promoting effects of PTH, the goitrogenic effect, and increased mitotic activity induced by hypercalcemia and neck irradiation." (PMID 34020602, 2021). "By the 10th week of gestation PTH is synthesised from fetal parathyroid glands, but circulating concentrations are kept low during fetal life due to relative hypercalcaemia dictated by the CaSR." (PMID 33614549, 2021). "The effect of hypercalcemia on impairing renal function and suppressing PTH hormone also leads to increased phosphate levels." (PMID 33732556, 2021). "Parathyroid carcinoma should be suspected when levels of PTH are high, in cases of severe hypercalcemia, and/or recurrent hypercalcemia." (PMID 35173680, 2021). "A widely accepted clinical definition of HPT is the concurrent demonstration of hypercalcemia and an elevated or inappropriately normal PTH." (PMID 33716975, 2021). "In most cases it is due to parathyroid hormone-related peptide (PTH-rp) production and the serum level of PTH is low in relation to hypercalcemia." (PMID 33839893, 2021).
Hypercalcemia (continued). "Laboratory tests showed severe hypercalcemia crisis with a serum calcium level of 5.21 mmol/L and a serum intact parathyroid hormone level of > 5000 pg/mL." (PMID 33429815, 2021). "Primary hyperparathyroidism (pHPT) is a common endocrine disorder, defined as hypercalcemia secondary to excessive secretion of parathyroid hormone by 1 or more hyperfunctioning parathyroid glands (HPGs)." (PMID 33917261, 2021). "Hyperparathyroidism is an endocrine condition with excess production of parathyroid hormone (PTH) by parathyroid glands and hypercalcemia." (PMID 34204387, 2021). "We report the case of a 6-years-old Italian male child with a personal history of bilateral nephrocalcinosis, severe hypercalcemia, increased urinary calcium/creatinine ratio and suppressed parathyroid hormone (PTH)." (PMID 33864587, 2021). "We observed a majority of biallelic mutations in CYP24A1, in accordance with our inclusion criteria (low serum PTH and medical history of hypercalcemia and/or hypercalciuria)." (PMID 34721296, 2021). "PHPT is characterized by elevated serum PTH concentration and hypercalcemia, with varying degrees of severity from asymptomatic to hypercalcemic crisis." (PMID 34420520, 2021). "This reflects the broad range of actions of PTH in target tissues as well as the myriad potential signs and symptoms of hypercalcemia per se." (PMID 33716975, 2021). "We describe the first case of severe hypercalcemia mediated by intact parathyroid hormone secretion from a bone metastasis of colorectal origin." (PMID 33413267, 2021). "Risk factors associated with the onset of calciphylaxis are: female gender, diabetesmellitus, warfarin use, obesity, hypoalbuminemia, and alterationsin mineral metabolism [hypercalcemia, hyperphosphatemia, and parathyroid hormone (PTH)extremes] (Evidence)." (PMID 34910803, 2021). "Hypercalcemia resulting from these conditions is non-PTH-mediated and therefore, PTH is expected to be suppressed." (PMID 34209340, 2021). "In CKD, there are multiple contributing factors to increased VC, such as hyperphosphatemia, hypercalcemia, and increased levels of parathyroid hormone (PTH)." (PMID 33917965, 2021). "In support of our results, previous studies have shown that severe hypercalcemia was common, and circulating PTH levels were physiologically suppressed in infantile HPP." (PMID 33827627, 2021). "Primary hyperparathyroidism is diagnosed in the presence of hypercalcemia and an elevated or inappropriately normal PTH level." (PMID 33918966, 2021). "Blood examinations revealed mild hypercalcemia (10.4 mg/dL, 8.8–10.1 mg/dL) and elevated serum levels of intact PTH (184.0 pg/mL, 10–65 pg/mL)." (PMID 33761720, 2021). "A defect in this process leads to a common biochemical profile, characterized by elevated 1,25-(OH)2D, absorptive hypercalcemia, hypercalciuria, nephrocalcinosis, or nephrolithiasis; and suppressed PTH." (PMID 34858904, 2021). "While hypercalcemia had been associated with cancer since the early twentieth century, it was Fuller Albright in 1941 who first postulated that this complication may be caused by tumor secretion of parathyroid hormone (PTH) or another similar factor due to its known roles in calcium homeostasis." (PMID 33828987, 2021). "Over the study period, we found attenuation of the biochemical profile, including improvement in hypercalcemia, decreasing 1,25-(OH)2D levels, and increasing depressed PTH levels." (PMID 34858904, 2021). "PHPT is an endocrinological disorder characterized by hypercalcemia and elevated serum parathyroid hormone (PTH), often with asymptomatic presentation." (PMID 34445560, 2021). "In another case, the hypercalcemia, elevated PTHrP, and suppressed PTH were promptly reversed after an urgent cesarean section, thereby indicating a placental origin of PTHrP." (PMID 33925967, 2021).